CLEC2D (C-type lectin domain family 2 member D)
Diseases named in the same sentence as CLEC2D in open-access papers:
CLEC2D is named in the same sentence as 60 diseases in open-access papers, as found by Europe PMC text mining. Sharing a sentence is not in itself a finding about the gene and the disease. The quoted sentences say what the papers report.
prostate carcinoma (14 papers, 2016 to 2026). A carcinoma that arises from epithelial cells of the prostate gland. "Overexpression of the CLEC2D gene in prostate cancer affects the biological process of the tumor." (PMID 35936781, 2022).
glioma (13 papers, 2019 to 2026). A benign or malignant brain and spinal cord tumor that arises from glial cells (astrocytes, oligodendrocytes, ependymal cells). "CD161, expressed in CD8+ T cells, interacts with CLEC2D to impair cytotoxic T-cell antitumor immunity in glioma and hepatocellular carcinoma." (PMID 40938562, 2026). "Immunohistochemical analyses have verified CLEC2D expression in glioma cells, demonstrating functional activation of this inhibitory axis in glioblastoma pathogenesis." (PMID 40895554, 2025). "Moreover, we observed significant interactions between KLRB1 (Tc) and CLEC2D (mBc1-4), which has recently been described to inhibit killing of glioma cells by T cells." (PMID 36153593, 2022). "In addition, downregulation of LLT1 using siRNA targeting CLEC2D enhanced NK cell lysis of glioma cells." (PMID 35185935, 2022). "In glioma, the CD161 - CLEC2D signaling pathway has been shown to attenuate the cytotoxicity of CD8+ T cells." (PMID 40895554, 2025). "In some types of cancer (i.e., TNBC, androgen-independent prostate cancer, glioma), CD161 appears to have immunosuppressive role, since tumor cells express C-Type Lectin Superfamily 2, Member D (CLEC2D) ligand and interaction between CD161 and CLEC2D hinders the cytotoxic activity of T cells." (PMID 36675137, 2023).
oropharyngeal squamous cell carcinoma (5 papers, 2020 to 2026). "Furthermore, CLEC2D was localized in the cytoplasm of oropharyngeal squamous cell carcinomas and ccRCC carcinomas." (PMID 40938562, 2026). "Interestingly, CLEC2D high-density expression on tumor-infiltrating lymphocytes (TILs) in oropharyngeal squamous cell carcinoma (OPSCC) correlates with the highest survival rates." (PMID 38675738, 2024).
breast carcinoma (4 papers, 2024 to 2026). "CLEC2D immunoreactivity was predominantly detected in the cytoplasm of breast cancer cells and was associated with increased proliferation and invasion, as well as poor clinical outcomes especially in those who had received chemotherapy." (PMID 40938562, 2026). "In summary, CLEC2D was overexpressed in breast cancer tissues and correlated with increased risk of recurrence of the patients, especially those who received chemotherapy." (PMID 40938562, 2026). "CD8+ T cells are key antitumor effectors, but exhausted CD8+ T cells (CD8Tex), in which CLEC2D has recently been identified as a hub gene in human breast cancer, are common in tumors." (PMID 40938562, 2026). "We subsequently examined the relationship between CLEC2D immunoreactivity and clinical outcomes, as assessed by disease-free survival and breast cancer-specific survival." (PMID 40938562, 2026). "CLEC2D immunoreactivity was observed in both the cytoplasm and cell membrane of breast carcinoma cells, while it was negligible in normal breast epithelium." (PMID 40938562, 2026). "CLEC2D immunoreactivity was significantly correlated with shorter disease-free (P = 0.0046) and breast cancer-specific survival (P = 0.033)." (PMID 40938562, 2026). "Here, we immunolocalized CLEC2D in 174 human breast carcinoma tissues and evaluated its clinical significance in breast cancer." (PMID 40938562, 2026). "In immunohistochemical analysis, CLEC2D immunoreactivity was predominantly detected in the breast cancer cells compared to normal breast epithelium, suggesting the possibility that CLEC2D has a pivotal role in breast cancer." (PMID 40938562, 2026). "In this study, we immunolocalized CLEC2D in 174 breast cancer tissues and correlated its immunoreactivity with clinicopathological parameters and clinical outcomes." (PMID 40938562, 2026). "Previous investigations have employed machine learning algorithms for molecular subtyping and prognostic model construction in breast cancer, identifying CRTAM, CLEC2D, and KLRB1 as pivotal hub genes associated with exhausted CD8+ T cell phenotypes." (PMID 40994935, 2025). "Additionally, we conducted in vitro studies to further investigate the NK cell-independent role of CLEC2D in breast cancer." (PMID 40938562, 2026). "Furthermore, CLEC2D was frequently expressed in breast cancer with neoadjuvant chemotherapy, and its expression was upregulated by EPI in MDA-MB-231 and T-47D cells, and by DTX in MCF-7 and MDA-MB-231 cells." (PMID 40938562, 2026). "CLEC2D was expressed on both the cytoplasm and cell membrane of breast cancer cells." (PMID 40938562, 2026). "Additionally, in the present study, cell proliferation and migration activity of breast cancer cell lines were significantly suppressed by CLEC2D knockdown." (PMID 40938562, 2026). "This might arise from the fact that CLEC2D not only suppresses antitumor effect of tumor-infiltrating lymphocytes but directly promotes breast cancer cell proliferation and migration." (PMID 40938562, 2026). "Therefore, the biological role of CLEC2D is still to be clarified in breast cancer." (PMID 40938562, 2026). "Taken together, CLEC2D might not only suppress the cytotoxic activity of immune cells but also directly promotes the proliferation and migration of breast cancer cells, thereby promoting breast cancer progression and recurrence." (PMID 40938562, 2026). "Thus, CLEC2D may promote breast cancer chemoresistance by inhibiting tumor-infiltrating immune cells." (PMID 40938562, 2026). "However, in the present study, we could not clarify the mechanisms underlying CLEC2D-related cell proliferation and migration in breast cancer." (PMID 40938562, 2026). "In vitro experiments demonstrated that the knockdown of CLEC2D significantly suppressed the proliferation and migration of MCF-7, MDA-MB-231, T-47D breast cancer cells." (PMID 40938562, 2026).
breast carcinoma (continued). "CLEC2D is induced by TLR3/4/7/8/9 ligands in immune cells, and these TLRs are also expressed in breast cancer cells." (PMID 40938562, 2026).
non-small cell lung carcinoma (4 papers, 2022 to 2026). A group of at least three distinct histological types of lung cancer, including non-small cell squamous cell carcinoma, adenocarcinoma, and large cell carcinoma. "In non-small cell lung cancer, CLEC2D is restricted to germinal center B cells in tertiary lymphoid structures, interacting with CD161+ CD4+ T cells to contribute to better outcomes." (PMID 40938562, 2026). "A meta-analysis revealed that the expression of CLEC2D (encoding LLT1) and KLRB1 (encoding CD161) genes was positively correlated with favorable prognosis in non-small cell lung cancer (NSCLC), independent of the extent of T-cell and B-cell infiltration." (PMID 40895554, 2025).
acute lymphoblastic leukemia (3 papers, 2023 to 2026). Leukemia with an acute onset, characterized by the presence of lymphoblasts in the bone marrow and the peripheral blood. "In addition, CLEC2D is elevated in immune cells of acute lymphoblastic leukemia but decreased in T cells after chemotherapy." (PMID 40938562, 2026).
leukemia (3 papers, 2022 to 2023). A malignant (clonal) hematologic disorder, involving hematopoietic stem cells and characterized by the presence of primitive or atypical myeloid or lymphoid cells in the bone marrow and the blood. "Some of the NK cell receptors are already found to be valuable for leukemia treatment and tumor surveillance, which were PD-1, 2B4 (CD244), CS1(CD319), LLT1 (CLEC2D) that regulate NK cell cytotoxicity, and NKp44, NKp30, and NKp46 known as natural cytotoxicity receptors (NCRs)." (PMID 37078002, 2022).
COVID-19 (2 papers, 2023 to 2025). A disease caused by infection with severe acute respiratory syndrome coronavirus 2. "What is more, LLT1-coding gene, CLEC2D, was shown to be one of 10 hub differentially expressed genes (DEGs) between COVID-19 ARDS and control group patients in the bioinformatics analysis of RNA-sequencing dataset of COVID-19 ARDS, obtained from GSE163426, Gene Expression Omnibus (GEO) database." (PMID 37287972, 2023).
endometriosis (2 papers, 2019 to 2021). The growth of functional endometrial tissue in anatomic sites outside the uterine body. "We also identified putative inhibitory interactions between endometriosis immune cells and ectopic FBs rather than eutopic FBs, including KLRB1, TIGIT, and PDCD1, which were highly expressed by NK and T cells, and potentially bind to CLEC2D, NECTIN3, and FAM3C, which were expressed by FBs." (PMID 34233737, 2021).
melanoma (2 papers, 2018 to 2024). A malignant, usually aggressive tumor composed of atypical, neoplastic melanocytes. "Further analyses showed that CLEC2D expression increases in peripheral blood CD4+ T cells in long-term survivor melanoma patients after vaccination." (PMID 38675738, 2024).
viral infection (2 papers, 2014 to 2015). "In addition, the gene CLEC2D, which reportedly encodes a natural killer receptor and is also induced on B cells upon viral infection, was also up-regulated." (PMID 25659141, 2015).
bladder cancer (1 paper, 2021). "GSDMB, CLEC2D, APOL2, TNFRSF14, and GBP2 were selected as prognostic genes in bladder cancer patients." (PMID 34708131, 2021).
cervical squamous cell carcinoma (1 paper, 2026). A squamous cell carcinoma arising from the cervical epithelium. "Similarly, TCGA analysis showed that CLEC2D expression was linked to improved prognosis in cervical squamous cell carcinoma." (PMID 40938562, 2026).
diabetes (1 paper, 2025). "Through the analysis involving differential gene expression and machine learning-based feature selection, we identified a subset of key genes, including CNOT1, KRT73, and CLEC2D, which consistently emerged across multiple models as potential biomarkers for early diabetes prediction." (PMID 40740938, 2025).
fungal infections (1 paper, 2023). "Thus, we predict that CLEC2D forms homodimers or heterodimers with TLR2 to negatively regulate IL-12 production during fungal infections." (PMID 37872182, 2023).
head and neck cancer (1 paper, 2020). A primary or metastatic malignant neoplasm affecting the head and neck. "This study is the first to investigate LLT1 expression (encoded by CLEC2D gene) in head and neck cancers to ascertain its impact on patient prognosis." (PMID 33255617, 2020).
kidney carcinomas (1 paper, 2020). Primary or metastatic malignant neoplasm involving the kidney. "CLEC2D expression was strongly and significantly associated with a poor prognosis in specific HNSCC subtypes (i.e., HPV-negative HNSCC) and kidney carcinomas (i.e., KIRC and KICH)." (PMID 33255617, 2020).
malaria (1 paper, 2020). Malaria is a serious and sometimes fatal disease caused by a parasite that commonly infects a certain type of mosquito which feeds on humans. "and, concomitantly, accelerates the malaria-induced decrease in Clec2d expression and increase in Clec2i expression." (PMID 33202767, 2020). "Vaccination, however, accelerates this malaria-induced decline of Clec2d, but significantly turns this decline to an increased expression towards the end of the crisis phase." (PMID 33202767, 2020). "Totally different to Clec2d, blood-stage malaria impairs early expression of Clec2i between day 0 and day 1 p.i., before inducing a continuous increase in expression, reaching a maximum on day 11 p.i." (PMID 33202767, 2020). "Only the genes Clec2d and Clec2i are responsive both to malaria and vaccination, though totally differently." (PMID 33202767, 2020). "Malaria induces increased expressions of Clec2d early on day 1 p.i., before expressions decline to lower levels towards the end of the crisis phase on day 11 p.i." (PMID 33202767, 2020).
skin cutaneous melanoma (1 paper, 2020). "In marked contrast, CLEC2D expression showed significant association with a good prognosis in HPV-positive HNSCC and skin cutaneous melanoma (SKCM) among others." (PMID 33255617, 2020).
tumor (45 papers, 2014 to 2026). "The role of CLEC2D in the tumor microenvironment likely depends on the cell types expressing CLEC2D and the presence of CD161-positive immune cells, accounting for its context-dependent prognostic significance." (PMID 40938562, 2026). "The scores of immunomodulatory interactions manifested a downgrade in tumor tissues, largely influenced by CLEC2D, CLEC2C, CLEC2B, and KLRB1." (PMID 40723292, 2025). "CLEC2D has been found to be expressed on tumor cells, infiltrating bone marrow cells, monocytes, natural killer (NK) cells, and subsets of T cells." (PMID 37872182, 2023). "FAM3C-related ligand-receptor pairs, like LAMP1_FAM3C, FAM3C_CLEC2D, CXADR_FAM3C, were slightly upregulated in ductal-tumor and malignant cells." (PMID 35087839, 2021). "The MCP-counter model was used to estimate the abundance of tumor-infiltrating NK cells in relation to CLEC2D expression." (PMID 33255617, 2020). "Taken together, CLEC2D in the cell membrane likely plays an important role in ligand binding, while internalized CLEC2D in the cytoplasm may also contribute to cytokine expression and activation of signaling pathways, potentially affecting tumor progression." (PMID 40938562, 2026). "First, we profiled the expression of several immunosuppressive receptor ligand genes, including CLEC2D, in CD138+ tumor cells from MM patients using bulk RNA‐seq data (MMRF‐CoMMpass cohort)." (PMID 40855628, 2025). "At the peak of CAR‐T expansion, strong activation signals and reduced CLEC2D expression might lead to CD161 downregulation and enable efficient tumor cell killing." (PMID 40855628, 2025). "Besides expression on tumor cells, CLEC2D mRNA and LLT1 protein have been detected in immune cells within the TME." (PMID 35185935, 2022). "However, it should be taken into account that CLEC2D mRNA levels may not strictly match with LLT1 protein expression/function and does not allow to distinguish between the tumor and the surrounding immune microenvironment." (PMID 33255617, 2020).
cancer (24 papers, 2010 to 2026). A tumor composed of atypical neoplastic, often pleomorphic cells that invade other tissues. "CLEC2D expressed on cancer cells suppresses antitumor effect of these cells by interacting with CD161 in human malignancies." (PMID 40938562, 2026). "Previous in vitro analysis has shown that CLEC2D is highly expressed in cancer cells and suppresses the cytotoxicity and cytokine production of NK cells by interacting with CD161." (PMID 40938562, 2026). "Expression of LLT1 by these cancer cell lines inhibited NK cell-mediated cytotoxicity which was restored by addition of blocking anti-LLT1 mAb or inactivation of CLEC2D gene." (PMID 35185935, 2022). "The CD161 activation was triggered by CLEC2D (C-type lectin domain family 2 member D) and suppressed the anti-cancer capacity of T cells." (PMID 35978433, 2022). "CD161 binds to Lectin-like transcript 1 (LLT1, also called CLEC2D or OCIL) that is broadly expressed on cells of the hematopoietic lineage, including B cell-derived cancer cell lines." (PMID 34503073, 2021). "The analysis of CLEC2D expression and patient survival among different cancers using the comprehensive web server resource TIMER 2.0 further revealed striking differences on prognosis." (PMID 33255617, 2020). "In addition, the interactions of KIR2DL3 and FAM3C, and KLRB1 and CLEC2D were detected between cancer cells and T & NK cells." (PMID 37945567, 2023). "In conclusion, this study uncovers the frequent LLT1/CLEC2D expression in HPV-negative OPSCC, unprecedentedly identified as an independent poor prognostic factor specifically for this cancer subtype." (PMID 33255617, 2020). "Given that CLEC2D induction requires robust and sustained immune activation, it would be interesting to investigate the potential of CD4+LLT1+ T cells as peripheral blood predictive biomarkers for immunotherapy responses and cancer remission." (PMID 38675738, 2024). "The non-specific mAb clone 4C7 was used but likely detected here LLT1/CLEC2D and not CLEC2A/KACL, as the latter has not been reported to be expressed in these cancers." (PMID 35185935, 2022).
infection (10 papers, 2014 to 2023). The state of being infected such as from the introduction of a foreign agent such as serum, vaccine, antigenic substance or organism. "We observed a higher number and frequency of NK cells, particularly those producing IFN-γ, in the kidneys of Clec2d-deficient mice compared to wild-type mice on Day 1 and 2 after infection with C. albicans." (PMID 37872182, 2023). "Consistently, the fungal burdens in the kidneys and brains of Clec2d-deficient mice were significantly lower than those in wild-type mice after infection for 2 and 4 days." (PMID 37872182, 2023). "Clec2d-deficient female mice are resistant to infection with Candida albicans, a human fungal pathogen, owing to the increase of IL-12 production and subsequent generation of IFN-γ-producing NK cells." (PMID 37872182, 2023). "We also found that the adoptive transfer of different MDSCs comparably increased the percentage of MDSCs in the lungs of Clec2d-deficient mice after infection with H99." (PMID 35835754, 2022). "More importantly, we showed that adoptive transfer of Clec2d-deficient MDSCs induced by GM-CSF plus GXM into wild-type mice significantly decreased their pulmonary fungi burden and Arg1 expression after infection with C. neoformans hypocapsular strain Cap59." (PMID 35835754, 2022).
metabolic disorders (1 paper, 2025). "Importantly, several of these genes (e.g., IRF2, SLC38A1, CLEC2D) have been previously implicated as potential biomarkers or functional mediators in autoimmune or metabolic disorders, supporting their relevance for early detection strategies." (PMID 40740938, 2025).
CLEC2D also shares sentences with these, for which no sentence is quoted: triple-negative breast carcinoma (8 papers); rheumatoid arthritis (7); glioblastoma (6); B-cell lymphomas (5); oral squamous cell carcinoma (4); hepatocellular carcinoma (3); lung carcinoma (3); malignant glioma (3); Arthralgia (2); Burkitt lymphoma (2); cervical cancer (2); cutaneous squamous cell carcinoma (2); Hodgkins lymphoma (2); lymph node metastasis (2); lymphoma (2); non-Hodgkin lymphoma (2); prostate tumors (2); spondyloarthropathy (2); acute T cell leukemia (1); Anxiety (1); asthma (1); bacterial infections (1); breast tumors (1); cholangiocarcinoma (1); chronic obstructive pulmonary disease (1); clear cell renal cell carcinoma (1); colon cancer (1); follicular lymphoma (1); hematological malignancies (1); hypopharyngeal cancer (1).
A further 7 diseases each share a sentence with CLEC2D in 1 paper.